KDM1A (lysine demethylase 1A)
Diseases named in the same sentence as KDM1A in open-access papers (continued):
Sharing a sentence is not in itself a finding about the gene and the disease.
atherosclerosis (5 papers, 2020 to 2025). A disease characterized by the build-up of fatty material and calcium deposition in the arterial wall resulting in partial or complete occlusion of the arterial lumen. "In this study, we presented a new perspective that lnc_000048 participated in atherosclerosis via epigenetic modifications caused by its interaction with KDM1A." (PMID 36689133, 2023). "We designed this study to explore the potential impact of histone modification induced by the interaction between lnc_000048 and KDM1A on plaque formation and stability in atherosclerosis, with the aim of identifying a new potential molecular mechanism underlying atherosclerosis progression." (PMID 36689133, 2023). "To investigate how lnc_000048 functions via KDM1A to induce atherosclerosis, we first evaluated the effect of the interaction between lnc_000048 and KDM1A on their expression levels." (PMID 36689133, 2023). "To elucidate the potential mechanism by which lnc_000048 promotes atherosclerosis, we focused on KDM1A, the key player in histone modification." (PMID 36689133, 2023). "More importantly, treating cells with KDM1A inhibitors can significantly accelerate the occurrence of inflammation, suggesting that targeting KDM1A can disturb the process of atherosclerosis." (PMID 36689133, 2023). "Our results indicated how lnc_0000048 promoted atherosclerosis and provide new potential strategies to target the lnc_000048 /KDM1A/MAP2K2/ERK axis to inhibit the progression of atherosclerosis." (PMID 36689133, 2023). "In our study, through RNA pull-down and mass spectrometry analyses, we found that lnc_000048 could bind KDM1A to participate in the development of atherosclerosis through histone modification." (PMID 36689133, 2023). "We hypothesized that lnc_000048 could interact with KDM1A in target genes’ promoter regions and thus involved in atherosclerosis." (PMID 36689133, 2023). "Although lncRNAs can recruit KDM1A to participate in histone methylation modification and regulate inflammation, cell proliferation, and other biological processes, little is known about the role of KDM1A-lncRNA interaction during atherosclerosis." (PMID 36689133, 2023). "However, the specific mechanisms by which lncRNAs interact with KDM1A during atherosclerosis initiation and development need to be further investigated." (PMID 36689133, 2023). "Considering the current status of knowledge in the field, one could predict that LSD1/KDM1A modulates atherosclerosis-relevant signaling pathways." (PMID 36552592, 2022). "Finally, we selected KDM1A, which participates in histone modification and might be involved in the development of atherosclerosis, as an lnc_000048-binding protein." (PMID 36689133, 2023). "Furthermore, to further determine whether the interaction between lnc_000048 and KDM1A contributes to the progression of atherosclerosis, we performed rescue experiments." (PMID 36689133, 2023). "Noteworthily, in addition to LSD1 (KDM1A), other archetypal KDM subtypes were found significantly up-regulated in human and experimental atherosclerosis." (PMID 36552592, 2022). "More importantly, our results suggested that lnc_000048 affected atherosclerosis progression by inhibiting KDM1A activity rather than its expression." (PMID 36689133, 2023).
cognitive deficits (5 papers, 2019 to 2025). "Second, loss-of-function mutations in both genes, KDM1A and PHF21A, cause rare neurodevelopmental disorders that involve cognitive deficits." (PMID 39395799, 2024).
Cushing syndrome (5 papers, 2022 to 2025). Cushing's syndrome (CS) encompasses a group of hormonal disorders caused by prolonged and high exposure levels to glucocorticoids that can be of either endogenous (adrenal cortex production) or exogenous (iatrogenic) origin. "This was suggestive of a potential different molecular predisposition, which was later elucidated in 2021 with the identification of KDM1A as the genetic cause of PBMAH associated with food-dependent Cushing’s syndrome." (PMID 39910635, 2025). "All patients with food-dependent Cushing's syndrome and KDM1A mutations in published studies were women." (PMID 40296186, 2025). "Recently, the other tumor suppressor gene, lysine (K)-specific demethylase 1A (KDM1A) was identified in PMAH associated with food-dependent Cushing’s syndrome." (PMID 36553033, 2022).
invasive ductal breast carcinoma (5 papers, 2012 to 2021). The most common type of invasive breast carcinoma, accounting for approximately 70% of breast carcinomas. "A previous report found that KDM1A expression differs significantly between ductal carcinoma in situ and invasive ductal carcinoma of the breast." (PMID 33799951, 2021).
kidney cancer (5 papers, 2020 to 2025). Primary or metastatic malignant neoplasm involving the kidney. "Meanwhile, it has been reported that KDM1A can regulate kidney cancer cell growth via epigenetic control of AR transcription factors and that KDM1A inhibitors may be good candidate drugs for treating kidney cancer." (PMID 34925656, 2021).
Thrombocytopenia (5 papers, 2017 to 2025). A reduction in the number of circulating thrombocytes. "In addition, disruption of the KDM1A–GFI1B complex by KDM1A inhibitors causes hematological toxicity such as thrombocytopenia." (PMID 36975603, 2023).
diffuse intrinsic pontine glioma (4 papers, 2017 to 2024). A neuroglial tumor that arises from the middle portion of the brain stem. "In diffuse intrinsic pontine glioma (DIPG) cells, histone demethylase KDM1A has been identified as a key chromatin regulator, with an important function in DIPG sensitivity to histone deacetylase inhibitors." (PMID 36497228, 2022).
diffuse large B-cell lymphoma (4 papers, 2021 to 2023). "Furthermore, in diffuse large B cell lymphoma (DLBCL), miR-101 regulates cell apoptosis by targeting lysine demethylase 1A (KDM1A) and MAPK kinase 1 (MEK1)." (PMID 36497343, 2022).
KBG syndrome (4 papers, 2017 to 2025). KBG syndrome is a rare condition characterized by a typical facial dysmorphism, macrodontia of the upper central incisors, skeletal (mainly costovertebral) anomalies and developmental delay. "In one study, clinical features are hypothesized to result from the combined effect of mutations in KDM1A and ANKRD11 (Ankrin Repeating Domain-Containing protein 11), the latter of which is associated with KBG syndrome involving craniofacial phenotypes." (PMID 33954026, 2021). "Additionally, a missense mutation in amine oxidase domain of KDM1A has been reported in patients with mixed features of KABUK1 and KBG syndrome (KBGS; OMIM 148050), which are characterized by macrodontia, distinctive craniofacial findings, and intellectual disability." (PMID 28665350, 2017). "A missense mutation in the amine oxidase domain of KDM1A has been reported in patients exhibiting mixed features of Kabuki syndrome (KABUK1) and KBG syndrome (KBGS; OMIM 148050), both of which are characterized by macrodontia, distinct craniofacial features, and IDD." (PMID 40469903, 2025).
myeloid leukemia (4 papers, 2019 to 2022). A clonal proliferation of myeloid cells and their precursors in the bone marrow, peripheral blood, and spleen. "In contrast, in another recent study it was shown that complete loss of KDM1A and expression of a catalytic inactive mutant of KDM1A resulted in differentiation of murine myeloid leukemia cells." (PMID 31649884, 2019).
neuroendocrine tumors (4 papers, 2022 to 2024). "For this reason, we have completed a clinical and mechanistic analysis of KDM5B in PCa cell lines, prostate adenocarcinoma and neuroendocrine tumor patient specimens and examined the effect of individual and cooperative inhibition of KDM1A and KDM5B on androgen regulated gene expression." (PMID 37152294, 2023). "Here we sought to extend the understanding of the individual and cooperative roles and clinical relevance of KDM1A and KDM5B in prostate adenocarcinoma and neuroendocrine tumor specimens." (PMID 37152294, 2023).
thyroid cancer (4 papers, 2020 to 2025). "In this study, we identified KDM1A as a stemness-associated histone methylation modifier in thyroid cancer that is related to the stem cell pluripotency and chemosensitivity of thyroid cancer in vitro and in vivo." (PMID 35198054, 2022). "To verify this mechanism in thyroid cancer, we constructed a KDM1A plasmid containing a K661A point mutation (i.e., a lysine-to-alanine mutation at lysine 661) to disrupt its demethylase activity." (PMID 35198054, 2022). "Lysine-specific demethylase 1A (LSD1/KDM1A), the first identified histone lysine demethylase, plays a critical role in thyroid cancer progression by regulating stemness and activating the Wnt/β-catenin signaling pathway." (PMID 40463874, 2025). "In this study, we identified KDM1A as an important epigenetic modifier that maintains the stemness of thyroid cancer through a mini histone methylation modifier screen." (PMID 35198054, 2022). "These mice displayed lower tumor volume and tumor-formation ability than control mice, indicating silence of KDM1A dramatically attenuated the stemness of thyroid cancer cells." (PMID 35198054, 2022). "The KDM1A-activated canonical Wnt pathway leads to increased cancer stemness and attenuated chemosensitivity in thyroid cancer." (PMID 35198054, 2022). "The results showed that multiple crucial signaling pathways and biological processes involved in tumorigenesis were regulated by KDM1A, suggesting that KDM1A plays essential roles in thyroid cancer development." (PMID 35198054, 2022). "Overexpression of KDM1A exhibited the opposite effects, suggesting that KDM1A was able toinduce EMT in thyroid cancer cells." (PMID 35198054, 2022). "In conclusion, KDM1A attenuates the chemosensitivity of thyroid cancer, and combining KDM1A inhibition with chemotherapy can achieve stronger antitumor effects." (PMID 35198054, 2022). "Inhibition of KDM1A attenuates cancer stemness and promotes thyroid cancer chemosensitivity in vitro and in vivo via inhibiting the Wnt/β-catenin signaling pathway." (PMID 35198054, 2022). "Taken together, these results suggested that KDM1A played essential roles in the stemness maintenance of thyroid cancer cells, thereby inducing dedifferentiation and promoting thyroid cancer progression." (PMID 35198054, 2022). "The results showed that the ALDEFLUOR bright population was positively regulated by KDM1A in thyroid cancer cells." (PMID 35198054, 2022). "Compared to normal thyroid cells, KDM1A was highly expressed in human thyroid cancer cells, especially in ATCs." (PMID 35198054, 2022). "The protein expression of HIF-1αwas significantly affected by KDM1A in thyroid cancer cells, but the mRNA level of HIF-1α was not regulated by KDM1A." (PMID 35198054, 2022). "Apart from the Wnt pathway and stem cell pluripotency, KDM1A can also influence many other important signaling pathways and biological properties of thyroid cancer, as detected in our RNA-seq results." (PMID 35198054, 2022). "We selected GSK-LSD1, a highly selective inhibitor targeting KDM1A to investigate its antitumor effects in thyroid carcinoma." (PMID 35198054, 2022). "GSK-LSD1, a KDM1A inhibitor, has demonstrated significant efficacy in inhibiting thyroid cancer progression and increasing chemotherapy sensitivity, suggesting potential clinical applications for advanced thyroid cancers." (PMID 40463874, 2025). "However, the role of KDM1A in CSCs and the therapeutic potential of KDM1A inhibitors for the treatment of the advanced thyroid cancer are poorly understood." (PMID 35198054, 2022). "Since CSC is a principal factor that determines the response to chemotherapy, we asked whether KDM1A could affect the sensitivity of thyroid cancer to chemotherapy." (PMID 35198054, 2022). "Furthermore, we also detected the global methylation levels of related histone markers in thyroid cancer cells and found that only the methylation of H3K4me1 and H3K4me2 was regulated by KDM1A." (PMID 35198054, 2022).
thyroid cancer (continued). "Furthermore, pharmacologic inhibition of KDM1A suppresses thyroid cancer progression and enhances the antitumor effects of chemotherapy." (PMID 35198054, 2022). "In summary, KDM1A can upregulate the Wnt/β-catenin signaling pathway in thyroid cancer cells by suppressing the ubiquitin-proteasome degradation of β-catenin and its regulation on APC2 and DKK1 may contribute to this process." (PMID 35198054, 2022). "The combination regimen of KDM1A targeted small molecule inhibitors and chemotherapy may provide an effective therapeutic strategy for patients with advanced thyroid cancer." (PMID 35198054, 2022). "All these data suggest that pharmacological inhibition of KDM1A by GSK-LSD1 can inhibit thyroid cancer progression and sensitize it to chemotherapy, and therefore, targeting KDM1A may bea novel therapeutic strategy for patients with advanced thyroid cancer." (PMID 35198054, 2022). "We further explored whether KDM1A regulated DKK1 expression through the HIF-1α/microRNA-146a axis in thyroid cancer." (PMID 35198054, 2022). "Additionally, we performed ALDEFLUOR assay to detect the activity of ALDH1 as well as CSCs enrichment, monitoring the change in CSC enrichment in thyroid cancer cells after KDM1A knockdown or overexpression." (PMID 35198054, 2022). "Importantly, we also demonstrate that GSK-LSD1, a highly selective inhibitor of KDM1A, significantly inhibits thyroid cancer progression and enhances the sensitivity of thyroid cancer to chemotherapy." (PMID 35198054, 2022). "Therefore, we hypothesize that KDM1A may contribute to the maintenance of thyroid cancer stemness and cancer dedifferentiation." (PMID 35198054, 2022). "To further confirm the regulation of KDM1A on the stemness properties of thyroid cancer, we used two independent shRNAs to suppress the expression of KDM1A in two ATC cell lines with relatively high endogenous KDM1A expression (CAL-62 and ACT1)." (PMID 35198054, 2022). "Therefore, silencing KDM1A may sensitize thyroid cancer to chemotherapy." (PMID 35198054, 2022). "All these results proved that KDM1A can regulate the transcription of DKK1 via HIF-1α/miR-146a axis; and then activate the Wnt pathway to promote the stemness and chemotherapeutic resistance of thyroid cancer." (PMID 35198054, 2022). "In addition, KDM1A knockdown also inhibited epithelial-mesenchymal transition (EMT), shown by increased E-cadherin and decreased N-cadherin, and decreased the migration and invasion capabilities of thyroid cancer cells." (PMID 35198054, 2022). "Intriguingly, we found that several histone demethylases such as KDM5B, KDM1A, KDM6B, KDM5A and KDM1B, were enriched in thyroid cancer spheres compared to non-CSCs." (PMID 35198054, 2022).
clear-cell renal cell carcinoma (3 papers, 2019 to 2023). "Recently, it was demonstrated that arborinine can block LSD1/KDM1A activity in clear-cell renal cell carcinoma ccRCC cell lines, sensitive or resistant to the kinase inhibitor sorafenib." (PMID 36840175, 2023).
developmental delay (3 papers, 2019 to 2021). "Haploinsufficiency of SIN3A and KDM1A mutations lead to similar syndromes characterized by the clinical features observed with RREB1 haploinsufficiency including developmental delay and craniofacial abnormalities." (PMID 32938917, 2020). "Most importantly, three boys with three different de novo heterozygous missense mutations in KDM1A have been reported, sharing craniofacial anomalies, developmental delay, and hypotonia." (PMID 31649809, 2019).
ductal carcinoma (3 papers, 2012 to 2019). "A study recently published by Serce and colleagues supports our results by showing that KDM1A expression gradually increases during tumor progression from pre-invasive neoplasia to fully invasive disease in ductal carcinoma of the breast." (PMID 24252778, 2013).
ductal carcinoma in situ (3 papers, 2012 to 2021). "KDM1A expression was also found to be significantly higher in high-grade ductal carcinoma in situ than in low-grade ductal carcinoma in situ." (PMID 33799951, 2021).
epilepsy (3 papers, 2017 to 2024). A brain disorder characterized by episodes of abnormally increased neuronal discharge resulting in transient episodes of sensory or motor neurological dysfunction, or psychic dysfunction. "As the IHC of epilepsy cohorts showed a consistent expression of KDM1A in astrocytes, in vitro validation of the role of KDM1A was assessed using PMA/Ionomycin stimulated fetal astrocytes (treatment at 3 h and 6 h)." (PMID 38467626, 2024).
Hepatic steatosis (3 papers, 2021 to 2025). Steatosis is a term used to denote lipid accumulation within hepatocytes. "In summary, our study discovered that KDM1A exacerbates hepatic steatosis and inflammation in NAFLD via increasing chromatin accessibility, further indicating the importance of harnessing chromatin remodeling and epigenetic alteration in combating NAFLD." (PMID 38295985, 2024). "The overexpression of Kdm1a exacerbated hepatic steatosis, inflammation, and fibrosis induced by a HFHC diet." (PMID 38295985, 2024). "In conclusion, our study reveals that KDM1A aggravates liver steatosis and inflammation through increasing the accessibility of chromatin, demonstrating that harnessing chromatin remodeling and epigenetic modifications is crucial for managing NAFLD." (PMID 38295985, 2024). "We here discovered that histone demethylase KDM1A exacerbates hepatic steatosis and inflammation in NAFLD via increasing chromatin accessibility, indicating harnessing chromatin remodeling and epigenetic alteration may be a potential way to combat NAFLD." (PMID 38295985, 2024). "In this study, we observed a remarkable upregulation of KDM1A in NAFLD and proved that KDM1A exacerbates hepatic steatosis and inflammation in NAFLD via increasing chromatin accessibility." (PMID 38295985, 2024).
metastatic disease (3 papers, 2018 to 2023). "Immunohistochemistry conducted on the retrospective cohort of CRC samples demonstrated a positive association between KDM1A expression in primary tumors and metastatic disease." (PMID 37385999, 2023).
prostate adenocarcinoma (3 papers, 2021 to 2023). "Our prior work identified lysine-specific demethylase 1 (LSD1; KDM1A) as a key driver promoting AR-independent survival of prostate adenocarcinoma (PRAD) cells." (PMID 37440313, 2023).
prostate tumor (3 papers, 2019 to 2021). "Likewise, in prostate tumour cells, direct methylation of KDM1A by the protein-methyltransferase EHMT2 facilitates an interaction between the chromatin remodeling proteins CHD-1 and KDM1A, that is necessary for androgen receptor dependent transcriptional activation." (PMID 33068438, 2020).
Arthritis (2 papers, 2025). Inflammation of a joint. "Accumulating evidence has elucidated the role of KDM1A in chondrocytes, positioning it as a potential therapeutic target for OA and other arthritic conditions as a potential target for the treatment of OA and other arthritis." (PMID 41291301, 2025).
cardiac hypertrophy (2 papers, 2022). "While LSD1/KDM1A and PHF8/KDM7B have a protective effect on cardiac hypertrophy." (PMID 36523510, 2022).
cyst (2 papers, 2014 to 2026). A sac-like closed membranous structure that may be empty or contain fluid or amorphous material. "Our study reveals the critical role of Kdm1a function in nephron development and highlights its affect on transcriptional programming for long-term renal function and susceptibility to cyst formation." (PMID 41797715, 2026). "CRISPR/Cas9-mediated KDM1A deletion in human kidney organoids caused cyst formation and altered gene expression, with snRNA-seq revealing downregulation of podocyte genes and upregulation of metabolic genes." (PMID 41797715, 2026).